VDR (vitamin D receptor)
Diseases named in the same sentence as VDR in open-access papers (continued):
Sharing a sentence is not in itself a finding about the gene and the disease.
osteosarcoma (21 papers, 2011 to 2025). A usually aggressive malignant bone-forming mesenchymal neoplasm, predominantly affecting adolescents and young adults. "Previously, we had demonstrated that AFB1 treatment in osteosarcoma cell line Saos-2 is associated with down-modulation of VDR expression at RNA and protein levels." (PMID 36066700, 2023). "Twenty-four hours of treatment with 1 μM ATRA caused changes in VDR mRNA levels and VDR protein levels in selected osteosarcoma cell lines." (PMID 32916897, 2020). "The synthesized compounds were evaluated in vitro for their binding affinity to the Vitamin D Receptor (VDR) and their transactivation potential in human osteosarcoma (HOS) cells." (PMID 40299638, 2025). "Calcitriol exerts its effects by binding to the vitamin D receptor (VDR) present in osteosarcoma cells, which in turn regulates the expression of various genes involved in cell proliferation, differentiation, and apoptosis." (PMID 39139816, 2024). "To gain a better understanding of SNAI2 and VDR regulation in osteosarcomas, we evaluated H3K27ac and H3K4me1 epigenetic alterations in a panel of highly metastatic and low metastatic human OS cell lines (GSE74230)." (PMID 37228489, 2023). "To study the effects of 1,25(OH)2D on metabolic and mt dysfunction, we used the vitamin D receptor (VDR)‐sensitive MG‐63 osteosarcoma cell model." (PMID 35079680, 2022). "Though not statistically significant (p = 0.058), 3 of 4 chondroblastic osteosarcomas expressed a high level of VDR (2+) compared to osteoblastic tumors (4/23)." (PMID 23346460, 2012). "Given these encouraging findings, this novel LCA derivative could form part of the arsenal in the treatment of cancers where expression of the VDR is evident, e.g., osteosarcoma." (PMID 39796220, 2025). "For better interpretation, we compared the two most different osteosarcoma cell lines—the Saos-2 reference cell line, which had the lowest level of RARα and the highest level of VDR, and the OSA-08 cell line, which had the highest level of RARα and the lowest level of VDR." (PMID 32916897, 2020). "In general, the results suggest that the levels of RARα and VDR in osteosarcoma cells could potentially be used as predictors of possible synergy between calcitriol and ATRA." (PMID 32916897, 2020). "Furthermore, this study provides the first evidence that ATRA treatment influences VDR expression in human osteosarcoma cells in vitro." (PMID 32916897, 2020). "Moreover, we provide the first evidence that ATRA is able to upregulate VDR expression in human osteosarcoma cells." (PMID 32916897, 2020). "The VDR and COL1A1 genes are required for proper bone formation and thus, if aberrations are present, could be associated with osteosarcoma." (PMID 21437228, 2011). "In a second study, the same group hypothesized that variants in the estrogen receptor (ESR1), vitamin D receptor (VDR), and/or collagen 1α1 (COL1A1) gene could be osteosarcoma risk factors." (PMID 21437228, 2011). "Initiation of VDR signaling facilitated the enrichment of EMT pathway genes, after which 1,25(OH)2D, the active vitamin D derivative, inhibited the EMT pathway in osteosarcoma subtypes." (PMID 37228489, 2023). "In this study, we assessed the impact of vitamin D and its receptor (VDR) on NMD-ROS-EMT signaling in in vitro and in vivo osteosarcoma animal models." (PMID 37228489, 2023). "It was shown that activation function 2 (AF-2; ligand-dependent domain localized on C-terminus of VDR) domain of human VDR interacts with suppressor for gal 1 (SUG1, component of the 26S proteasome) in ROS17/2.8 cell line (rat osteosarcoma)." (PMID 28427151, 2017). "Parathyroid hormone or cAMP (both activators of PKA) up-regulated VDR and augmented the 1,25(OH)2D-dependent induction of CYP24A1 and osteopontin after 9 h treatment in UMR-106 cell line (rat osteosarcoma)." (PMID 28427151, 2017).
osteosarcoma (continued). "According to our results, the endogenous levels of RARα and VDR could be used as a predictor of possible synergy between ATRA and calcitriol in osteosarcoma cells." (PMID 32916897, 2020). "Lisse’s team recently found that, in the vitamin D receptor (VDR)-sensitive MG 63 osteosarcoma cell model, vitamin D treatment can promote the depolarization of the mitochondria membrane to reduce mitochondrial ROS, thereby controlling the growth of osteosarcoma cells." (PMID 39061897, 2024).
polycystic ovary syndrome (21 papers, 2013 to 2025). A disorder that manifests as multiple cysts on the ovaries. "Vitamin D receptor (VDR) gene polymorphisms have been implicated in polycystic ovary syndrome (PCOS)." (PMID 39866289, 2025). "Characteristics of included studies on vitamin D receptor gene polymorphisms and polycystic ovary syndrome risk." (PMID 30687119, 2018). "The results of case-control studies on the association between vitamin D receptor gene (VDR) polymorphisms and polycystic ovary syndrome (PCOS) are inconclusive." (PMID 35958959, 2022). "Its deficiency has also been found among patients with polycystic ovary syndrome (PCOS), and it could be attributed to the polymorphisms in the vitamin D receptor (VDR) gene." (PMID 40376337, 2025). "Vitamin D and insulin play an important role in susceptibility to polycystic ovary syndrome (PCOS), and therefore vitamin D receptor (VDR), parathyroid hormone (PTH), and insulin receptor (INSR) gene variants might be involved in the pathogenesis of PCOS." (PMID 27141540, 2015).
ulcerative colitis (21 papers, 2010 to 2025). An inflammatory bowel disease involving the mucosal surface of the large intestine and rectum. "Lactobacillus rhamnosus GG (LGG) has shown promising results in ulcerative colitis (UC) patients, but its effect on the VDR pathway remains unexplored in humans." (PMID 41304896, 2025). "The H19-miR675-5p-VDR pathway increases VDR expression level in AS, but in ulcerative colitis, H19 overexpression decreased VDR expression through the same pathway." (PMID 38475720, 2024). "This highlights the VD/VDR-Notch pathway as a potential new therapeutic target for protecting the intestinal barrier against ulcerative colitis." (PMID 39130644, 2024). "Previous findings reported that VDR protein expression in the colonic mucosa of ulcerative colitis patients was significantly lower than the normal colon mucosa." (PMID 36341397, 2022). "In patients with ulcerative colitis, none of the VDR polymorphisms were associated with hospitalization in the univariate analysis." (PMID 40076474, 2025). "The current work was not designed for hypothesis testing but rather as a proof-of-concept investigation aimed at exploring the feasibility of probiotic-induced VDR modulation in ulcerative colitis." (PMID 41304896, 2025). "Furthermore, in ulcerative colitis patients, the inflamed intestine had low VDR and increased Claudin-2." (PMID 36678175, 2023). "ZNF91, VDR, DLEU1, SATB2-AS1, and TP53TG1 in ulcerative colitis are related to the regulation of PPAR, AMPK, and metabolic signaling pathways." (PMID 39791702, 2024). "MiR-222-3p targets SOCS1 to aggravate the inflammatory response by suppressing VDR and activating STAT3 signaling in ulcerative colitis." (PMID 35946880, 2022). "Additionally, miR-222-3p expression was upregulated in ulcerative colitis patients (P = 5.16E−10), while SOCS1 (P = 2.75E−10) and VDR (P = 52.5E−9) expression was downregulated in ulcerative colitis patients." (PMID 35946880, 2022).
acute kidney injury (20 papers, 2005 to 2025). Sudden and sustained deterioration of the kidney function characterized by decreased glomerular filtration rate, increased serum creatinine or oliguria. "In our previous studies, we demonstrated that 1, 2, 5(OH)2D3 (active vitamin D) or its active analogs can exert renal protection in lipopolysaccharide (LPS)-induced acute kidney injury by activating VDR." (PMID 36909229, 2023). "The interaction between renal VDR and NF-κB p65 provides a mechanistic explanation for VitD3-mediated anti-inflammatory activity during LPS-induced acute kidney injury." (PMID 26691774, 2015). "As expected, VitD3 pretreatment reinforced the interaction between renal VDR and NF-κB p65 during LPS-induced acute kidney injury." (PMID 26691774, 2015). "The interaction between renal VDR and NF-κB p65 subunit provides a mechanistic explanation for VitD3-mediated anti-inflammatory activity during LPS-induced acute kidney injury." (PMID 26691774, 2015). "Interestingly, it has been shown that the suitable activation of VDR is protective against cisplatin-induced acute kidney injury (AKI) through preventing ferroptosis." (PMID 40296902, 2025). "In both mouse models of acute kidney injury (AKI) and renal tissues from AKI patients, there is a persistent downregulation of VDR expression." (PMID 40880413, 2025). "VD/VDR signaling down-regulated the expression of pyroptosis associated markers NLRP3, GSDMD-N, Cleaved Caspase-1 and mature IL-1βin AKI models, and partially alleviated cisplatin induced acute kidney injury by inhibiting pyroptosis mediated by NF-κB." (PMID 37483634, 2023). "Our preliminary work has revealed that vitamin D receptor (VDR) activation is protective against cisplatin induced acute kidney injury (AKI)." (PMID 31996668, 2020). "Previous studies have reported that VDR can regulate ferroptosis via GPX4 in cognitive dysfunction and acute kidney injury." (PMID 36846715, 2023). "The present study does not exclude the role of VDR in both adaptive and innate immune cells on VitD3-mediated anti-inflammatory effect in LPS-induced acute kidney injury." (PMID 26691774, 2015). "This discrepancy could possibly arise from the important role VDR, CaR and FGF-23 play in the maintenance of calcium and phosphorus homeostasis which is strongly perturbed in the model of renal failure." (PMID 21695192, 2011).
Allergy (19 papers, 2005 to 2025). An allergy is an immune response or reaction to substances that are usually not harmful. "Genotype distributions of CYP2R1, GC, and VDR polymorphisms in patients with allergy symptoms, autism spectrum disorder, and Hashimoto’s thyroiditis." (PMID 41340975, 2025). "For VDR variants, genotypes of ApaI (rs7975232), BsmI (rs1544410), and TaqI (rs731236) were relatively more frequent in the allergy and ASD groups, suggesting a tendency toward heterozygosity for risk alleles in these populations." (PMID 41340975, 2025). "Overall, analysis of VDR polymorphisms revealed higher frequencies of risk allele carriers in the allergy group (for FokI, BsmI, and TaqI variants), whereas only the ApaI variant showed a higher carrier rate in the ASD group." (PMID 41340975, 2025). "In the VDR BsmI (rs1544410) genetic variant, one of the allergy patients has the homozygous (AA) genotype, and five have the heterozygous (AG) genotype." (PMID 38807972, 2024). "In our study, seven of the allergy patients have the homozygous (CC) genotype and one has the heterozygous (AC) genotype in the VDR FokI (rs2228570) variant." (PMID 38807972, 2024). "The Vitamin D receptor (VDR) genetic variants and microbiota diversity (using the Firmicutes/Bacteroides ratio, an indicator of dysbiosis) of 11 cases (9 allergy and two autism patients) participating in the study were evaluated together." (PMID 38807972, 2024). "Considering the VDR TaqI (rs731236-C) variant, five of the allergy patients have the heterozygous (CT) genotype, and only one case has the homozygous (CC) genotype." (PMID 38807972, 2024). "In the VDR BsmI genetic variant, one of the allergy patients has the homozygous (AA) genotype, and five have the heterozygous (AG) genotype." (PMID 38807972, 2024). "Five of the allergy patients are at risk with the heterozygous (CT) VDR TaqI variant, and one carries the homozygous (CC) genotype." (PMID 38807972, 2024). "While 6 of the allergy patients carry the homozygous (CC) genotype in the VDR FokI (rs2228570-C) variant, three have the heterozygous (AC) genotype." (PMID 38807972, 2024). "When looking at the VDR ApaI (rs7975232) genetic variant, five of the allergy patients have the heterozygous (AC) genotype, and four have the homozygous (AA) genotype." (PMID 38807972, 2024). "Seven of the allergy patients have the homozygous (CC) genotype, and one has the heterozygous (AC) genotype for the VDR FokI variant." (PMID 38807972, 2024). "While five of the allergy patients have the heterozygous (CT) genotype in the VDR TaqI (rs731236) variant, one carries the homozygous (CC) genotype." (PMID 38807972, 2024). "Five of the allergy patients had a heterozygous (AC) genotype in the VDR ApaI (rs797522-C) variant, and one carried a homozygous (CC) genotype." (PMID 38807972, 2024). "The VDR polymorphisms and their associations with allergic diseases were intensively studied by various research groups, however, the results were inconsistent possibly due to differences in methodology or the populational bias." (PMID 34343413, 2021). "Mutations in the VDR gene have been associated with colorectal cancer,precocious puberty, atopic dermatitis, and other allergic diseases in certainpopulations." (PMID 30066819, 2018). "Five of the other seven traits identified that associated with VDR peaks had predominant immune phenotypes including Helicobacter pylori serologic status, self-reported allergy and Celiac disease." (PMID 28166722, 2017). "The relationship between vitamin D and allergic diseases has increasingly attracted attention in recent years, and accordingly, SNPs of VDR and CYP2R1 have also been reported to be associated with some immune disorders." (PMID 26177022, 2015).
Allergy (continued). "In the allergy group, heterozygous genotypes (such as AG or CT) were more prevalent across most VDR variants (except FokI), suggesting comparatively greater genetic diversity relative to the more homozygous-dominant profiles observed in the Hashimoto’s thyroiditis and ASD groups." (PMID 41340975, 2025). "Polymorphisms in the VDR, particularly single-nucleotide polymorphisms (SNPs) such as rs1544410 and rs2228570, have been frequently studied in the context of allergic diseases due to their potential impact on receptor function and downstream vitamin D activity." (PMID 41157208, 2025). "In our study, the findings related to VDR FokI and TaqI variants observed in Hashimoto’s thyroiditis (FokI: 90%, TaqI: 50%), allergic diseases (FokI: 92.1%, TaqI: 71.1%), and ASD (FokI: 91.7%, TaqI: 66.7%) suggest that environmental and immunological factors play important roles in these conditions." (PMID 41340975, 2025). "Point mutations of the VDR-coding gene could influence the function of this receptor; thus, these polymorphisms could cause susceptibility to various allergic diseases, including BA." (PMID 38339221, 2024). "Genetic variants of VDR have been studied as a probable factor for autoimmune and allergic diseases as they might affect VDR activity." (PMID 34343413, 2021). "In addition, meta-analysis study revealed that VDR rs7975232, rs1544410 and rs731236 gene polymorphisms may confer susceptibility to allergic diseases in certain populations." (PMID 37407930, 2023). "In contrast, VDR FokI (rs2228570) exhibited a more balanced and homozygous-dominant distribution across the allergy, ASD, and Hashimoto’s groups, indicating broader genetic diversity rather than group-specific clustering." (PMID 41340975, 2025). "Minor local variations were observed for VDR (BsmI), VDR (FokI), and GC (rs7041); specifically, certain genotype combinations appeared slightly more frequent in the allergy group." (PMID 41340975, 2025). "Genetic studies have provided early evidence of a potential role of the VDR in the genesis of allergic diseases." (PMID 35625670, 2022). "While there is no risk allele in the VDR BsmI (rs1544410-A) variant for autism patients, six of the allergy patients carry the heterozygous (AG) genotype." (PMID 38807972, 2024). "When examining the relationships between allergic diseases and the VDR rs2228570 FokI polymorphism, no positive result was detected for this polymorphism." (PMID 38807972, 2024). "Interestingly, polymorphisms in the vitamin D receptor (VDR) gene such as the SNPs rs1544410 and rs2228570 alter VDR function and have been frequently studied in association with allergic diseases." (PMID 34062998, 2021). "In addition, the VDR and CYP2R1 genes map to chromosome 12q and 11p respectively, and both of these chromosome locations include susceptibility loci for allergic diseases according to genome-wide linkage analysis studies." (PMID 26177022, 2015). "However, other studies could not confirm the role of VDR polymorphisms on allergy outcome." (PMID 35625670, 2022).